E2F1 (E2F transcription factor 1)
Diseases named in the same sentence as E2F1 in open-access papers (continued):
Sharing a sentence is not in itself a finding about the gene and the disease.
glioma (continued). "Keeping in mind that PTTG1 can mediate glioma cell proliferation, the signaling cascade ECT2/PMSD14/E2F1/PPT11G could be potentially targeted as a therapeutic approach." (PMID 35409080, 2022). "Finally, we highlight the intimate link between high STAT3 signaling, E2F1 and H2AZ2 expression in glioma patients." (PMID 35058574, 2022). "In gliomas, the levels of HELLS are regulated by the LRP6-GSK3b-E2F1 axis." (PMID 36012581, 2022). "Synergized with E2F1, CDCA8 promoted glioma cell proliferation and migration in vitro and vivo." (PMID 33542211, 2021). "Moreover, we identified a set of TFs which putatively regulate gene expression in multiple TADs, including known glioma related TFs such as REST, E2F1 and NFKB1." (PMID 34341417, 2021). "Moreover, FER1L4/miR-372/E2F transcription factor 1 (E2F1) is a competing endogenous RNA (ceRNA) system that regulates the proliferation and cell-cycle distribution in glioma cells." (PMID 33868788, 2021). "BIP-MPC-NP attenuated E2F1 expression by interactions between TTP and ARE motifs within the E2F1 3′-UTR and consequently downregulated DNA damage repair and enhanced TMZ chemosensitivity in TMZ-resistant glioma." (PMID 32001707, 2020). "In the glioma, DLX6-AS1 accelerated the carcinogenesis via suppressing miR-197-5p to suppress E2F1." (PMID 31787849, 2019). "Importantly, we found that knock-down of FBXW7 increases the levels of several cell cycle proteins, such as E2F1, LSH, KI67, Cyclin A2 and Cyclin E2, both in basic conditions, as well as in miR-10b – depleted glioma cells." (PMID 25738367, 2015). "Importantly, western blotting analysis showed that ectopic expression of miR-329 dramatically decreased, but inhibition of miR-329 increased E2F1 protein expression in both LN18 and T98G glioma cells." (PMID 23866847, 2013). "However, the interplay between ATAD2 and E2F1 in regulating PDK1 expression in glioma is not yet fully understood." (PMID 41158756, 2026). "There was a significant association between H2AZ2 and E2F1 (but not E2F4), suggesting that E2F1 may be co-expressed with H2AZ2 in glioma." (PMID 35058574, 2022). "Mechanistically, E2F1 binds to the promoter region of FGF14-AS2, forming the FGF14-AS2/miR-320a/E2F1 feedback loop which may offer potential target for precision therapy against glioma." (PMID 34659533, 2021). "Also, C-EBPα and E2F1 levels were not altered by irradiation in both glioma and normal brain tissues." (PMID 29100427, 2017). "In non-small cell lung cancer, GCN5 was proved to be recruited by E2F1 to E2F1-binding sites to regulate downstream target expression, but it turned out that down-regulation of GCN5 did not cause significant change of E2F1 expression in glioma cells." (PMID 26378521, 2015).
hepatocellular carcinoma (94 papers, 2009 to 2026). A malignant tumor that arises from hepatocytes. "Upregulation of PSMD14, in hepatocellular carcinoma, has been associated with tumor promotion through E2F transcription factor 1 (E2F1) stabilization and its target genes." (PMID 33805973, 2021). "E2F1 seems to be a promising regulator in ovarian carcinoma and early studies suggest that E2F1 was significantly overexpressed in hepatocellular carcinoma and played a causative relationship with cell proliferation." (PMID 30050877, 2017). "The suppression of ARID2 expression in hepatoma cells facilitated G1/S transition associated with transcriptional upregulation of E2F1, cyclin D1, and cyclin E1, induction of CDK4, and phosphorylation of Rb." (PMID 27351279, 2016). "Moreover, miR-1205 was associated with sorafenib resistance in hepatocellular carcinoma by interacting with circFN1 and E2F1." (PMID 34899853, 2021). "It has been shown to be upregulated in hepatocellular carcinoma and act as an oncogene through association with RNA binding protein E2F1 in NSCLC cells, suggesting that this lncRNA-HIT may exert its biological function by functionally associating with transcription factors." (PMID 35132340, 2022). "Survival analysis indicated that the expression levels of CCNA2, CHK1, E2F1, and TOP2A are significantly associated with the survival prognosis of hepatocellular carcinoma patients, with p-values of 0.0038, 0.00013, 0.013, and 0.00066, respectively." (PMID 40573296, 2025). "More intriguingly, E2F1 plays a crucial role in activating the PI3K/AKT/mTOR signaling pathway in hepatocellular carcinoma cells." (PMID 39991770, 2025). "Our findings are consistent with previous research showing that E2F1 can transactivate STMN1 expression in hepatocellular carcinoma, reinforcing the regulatory relationship between the RB/E2F1 axis and STMN1." (PMID 39776361, 2025). "The expression levels of MYBL2 were positively correlated with those of E2F1 in hepatocellular carcinomas, and downregulation of E2F1 in hepatocellular carcinoma cells reduced MYBL2 expression." (PMID 39613162, 2024). "Supporting this, prior research has shown that E2F1 can transactivate STMN1 expression in hepatocellular carcinoma, further supporting the regulatory relationship between the RB/E2F1 axis and STMN1." (PMID 39711570, 2024). "For instance, in hepatocellular carcinoma (HCC), SNHG3 regulates NEIL3 expression through transcription factor E2F1, implicating it as a potential diagnostic marker and therapeutic target." (PMID 39349640, 2024). "API-5 was found to inhibit apoptosis of hepatoma cells through NF-κB pathway, and E2F1-dependent apoptotic pathway." (PMID 38143869, 2023). "In this study, we explored the interaction mechanism among HBx, miR-187-5p and transcription factors E2F1 and FoxP3 in hepatocellular carcinoma cells." (PMID 37531206, 2023). "In line with this, a recent study has identified the increased expression of E2F1 in human NAFLD, and that increased E2F1 can function as a metabolic driver of NAFLD-related hepatocellular carcinoma." (PMID 36777627, 2023). "SETD7 is known to stabilize E2F transcription factor 1 (E2F1) in hepatocellular carcinoma, leading to the expression of cyclin E1, cyclin A2, and CDK1, which triggers the cell cycle in tumorigenesis." (PMID 38036730, 2023). "In individuals with liver cancer, STMN1 expression was significantly correlated with E2F1/TFPD1 and KPNA2 expression and was associated with poor prognosis in patients with hepatocellular carcinoma." (PMID 36127700, 2022). "During hepatocellular carcinoma progression, E2F1 promoted the expression of its genes involved in glycolysis, which contributed to the Warburg effect." (PMID 35689245, 2022). "MicroRNA-34a inhibits the invasiveness of hepatocellular carcinoma by inhibiting the expression of E2F1." (PMID 36699068, 2022).
hepatocellular carcinoma (continued). "On the other hand, E2F1 exhibits antiapoptotic activity in human and rodent hepatoma via its capacity to offset c-Myc-induced apoptosis." (PMID 35844791, 2022). "The E2F1/USP11 positive feedback loop promotes hepatocellular carcinoma metastasis and inhibits autophagy by activating the ERK/mTOR pathway." (PMID 35383175, 2022). "The abnormal expression of E2F1 in hepatocellular carcinoma leads to tumor cell proliferation and invasion." (PMID 36699068, 2022). "Celastrol induces apoptosis and inhibits the proliferation of hepatocellular carcinoma cells by downregulating E2F1." (PMID 36699068, 2022). "We found that knockdown of E2F1 inhibited the proliferation ability and G1/S transition of hepatoma cells, whereas overexpression of E2F1 produced the opposite effects." (PMID 35844791, 2022). "CDCA5 was transcribed by E2F1 in hepatocytes, promotes tumorigenesis by enhancing cell proliferation and inhibiting apoptosis of hepatocellular carcinoma through the AKT pathway, and was significantly related to the poor prognosis of liver cancer patients." (PMID 33190424, 2021). "These in vivo data support the conclusion from in vitro cell models that upregulation of lnc‐APUE, resulting from HNF4α downregulation, promotes hepatoma growth by upregulating the E2F1 level." (PMID 33854885, 2021). "The expression levels of SHH, E2F1, and lipogenic molecules were checked at different stages of hepatocellular carcinoma." (PMID 32577158, 2020). "It has been shown that TFDP1, together with E2F1, is involved in regulating hepatocellular carcinoma cells through a knockdown experiment that confirmed a physical interaction of KPNA2 with E2F1 and TFDP1." (PMID 33124660, 2020). "In hepatocellular carcinoma cells, E2F1 promotes cell proliferation and suppresses apoptosis by inducing c-Myc expression and upregulating SKP2 expression." (PMID 31327760, 2019). "PEG10 is reported to be directly regulated by E2F-1 in hepatocellular carcinoma and neuroendocrine prostate cancer." (PMID 28193232, 2017). "HULC increased the expression of E2F1 in hepatoma cells and levels of HULC were positively correlated with those of E2F1 in HCC tissues." (PMID 26540633, 2016). "To investigate the relationships between HULC and E2F1, we evaluated the expression levels of E2F1 in hepatoma cells." (PMID 26540633, 2016). "Mechanistically, HULC activated the promoter of SPHK1 in hepatoma cells through the transcription factor E2F1." (PMID 26540633, 2016). "HULC activates the transcription of SPHK1 through transcriptional factor E2F1 in hepatoma cells, leading to up-regulation of SPHK1." (PMID 26540633, 2016). "In the liver, apoptotic activity induced by forced E2F1 expression alone or HBX expression also showed the apoptotic role of E2F1 in hepatoma tumorigenesis." (PMID 27175585, 2016). "As expected, we revealed that miR-107 was able to bind the 3′UTR of E2F1 mRNA in hepatoma cells, resulting in the down-regulation of E2F1." (PMID 26540633, 2016). "In contrast, short hairpin RNAi-mediated attenuation of ISX and E2F1 decreased cell proliferation and malignant transformation, respectively, in hepatoma cells in vitro and in vivo." (PMID 27175585, 2016). "Hepatoma cells (SK-Hep1) that were cotransfected with deletion mutants of the E2F1 promoter (positions delta−117 to −133) and pEGFP/c1-ISX lost the luciferase activity induced by ISX." (PMID 27175585, 2016). "The expression of genes encoding proteins known to be associated with the cell cycle (E2F1), adhesion and proteolysis (OPCML) and hepatocellular carcinoma (FZD7, IGFBP1 and LEF1) was elevated 3- to 9-fold." (PMID 26442469, 2015).
hepatocellular carcinoma (continued). "A link between E2F1 and the mTORC1 pathway has been recently suggested in E2F1 transgenic mouse and human hepatocellular carcinomas (HCC)." (PMID 21283628, 2011). "This discordance between E2F1 and TFDP1 protein levels was also described in non-Hodgkin lymphomas and in hepatocellular carcinomas, where only TFDP1 overexpression was associated with a larger tumor size." (PMID 19995430, 2009). "Additionally, the E2F1/DDX11 axis is capable of promoting malignant behaviors of hepatocellular carcinoma cells via activation of the PI3K/AKT/mTOR signaling pathway." (PMID 36777627, 2023). "Mediated by E2F1, SLC16A1-AS1 could progress bladder cancer to the invasive stage and serve as a new diagnostic indicator in hepatocellular carcinoma." (PMID 35223846, 2022). "Moreover, E2F1/USP11 further facilitates the progression of hepatocellular carcinoma by regulating the ERK/mTOR pathway to inhibit autophagy." (PMID 35715413, 2022). "Furthermore, lnc‐APUE accelerated G1/S phase transition and hepatoma cell growth by acting as a miR‐20b sponge to upregulate E2F1 expression." (PMID 33854885, 2021). "Besides, genes down‐regulated in the diethylnitrosamine treatment‐induced or E2F1 overexpression‐induced hepatocellular carcinoma models and HNF1A knockout model of type 1 diabetes are also overrepresented, supporting the liver protective roles of metformin." (PMID 32529766, 2020). "Moreover, in hepatocellular carcinoma cells, expression of several glycolytic enzymes genes is enhanced by E2F1-induced Pontin/Reptin helicases complex recruitment to E2F target genes." (PMID 31627130, 2019). "Hepatoma cells treated with ISX or E2F1 shRNAi showed significant decreases in growth rate (69% and 43%, respectively, according to cell counts at 72 h cultivation; 44% and 25%, respectively, according to the BrdU incorporation assay) from those observed in cells with pEGFP controls." (PMID 27175585, 2016). "Therefore, our results indicate that E2F1 is an important downstream gene of ISX in hepatoma progression." (PMID 27175585, 2016). "Interestingly, our data show that HULC is capable of promoting tumor angiogenesis through miR-107/E2F1/SPHK1 signaling in hepatoma cells." (PMID 26540633, 2016). "CircFN1 mediates sorafenib resistance through the miR-1205/E2F1 axis in hepatocellular carcinoma (HCC)." (PMID 37160894, 2023). "In hepatocellular carcinoma (HCC) and nasopharyngeal carcinoma, the expression of E2F1 and STMN1 was correlated with each other both at mRNA and protein levels." (PMID 35186166, 2022). "Centromere protein U (CENPU) has been shown to accelerate the G1/S transition of hepatocellular carcinoma cell proliferation by interacting with E2F6 and affecting transcription of E2F1." (PMID 37292517, 2023). "For instance, the overexpression of E2F1, E2F2, and E2F3 was observed in patients with hepatocellular cancer, bladder cancer, retinoblastoma, and liposarcoma." (PMID 35392496, 2022). "CDCA5, transcribed by E2F1, potentiates the initiation of tumor by enhancing cell proliferation and inhibiting apoptosis via the AKT pathway in hepatocellular carcinoma." (PMID 32733928, 2020). "Our results corroborated these findings in hepatocellular carcinoma model and notably, we also found a strong positive correlation between the SHH expression and the expression of E2F1, FASN, and SREBP1c." (PMID 32577158, 2020). "Fucoidan from U. pinnatifida (commercially available or laboratory prepared) targeted p21Cip1/Waf and E2F-1 in PC-3 cells and cyclin D1 and CDK4 in mouse hepatoma Hca-F cells." (PMID 32046368, 2020). "HULC promotes tumor angiogenesis in liver cancer through miR-107/E2F1/SPHK1 signaling and modulates abnormal lipid metabolism in hepatoma cells through a miR-9-mediated RXRA signaling pathway." (PMID 28427159, 2017).
hepatocellular carcinoma (continued). "The E2F1 promoter region between −168 and +31 was pulled down by an anti-ISX antibody and was shown to correlate with the expression level of E2F1 in hepatoma cells, particularly in Hep3B and SK-Hep1 cells." (PMID 27175585, 2016). "HULC increased the expression of E2F1 in hepatoma cells and the levels of HULC were positively related to those of E2F1 in clinical HCC samples." (PMID 26540633, 2016). "Hepatoma cells co-transfected with shRNA is against both ISX and E2F1 showed more significant downregulation of proliferation- and anti-apoptotic signaling markers, but increased expression of apoptotic and autophagic signaling markers." (PMID 27175585, 2016). "Hepatoma cells (SK-Hep1 and Huh 7) transfected with ISX shRNAi showed significant downregulation of E2F1 and DP1 protein expression as well as of proliferation markers (cyclin D1, c-Myc, Cdc25A, and PCNA) and anti-apoptotic genes (p65 and Mcl-1)." (PMID 27175585, 2016). "Apoptotic and autophagic signaling were significantly downregulated in hepatoma cells co-transfected with ISX and E2F1 relative to that in the cells transfected with either ISX or E2F1." (PMID 27175585, 2016). "In hepatocellular carcinoma research, it had been observed that USP11 might stabilize the protein level of the transcription factor E2F1, and E2F1 could also stimulate the transcription and translation of USP11." (PMID 39617751, 2024). "For example, NANOG is induced by toll-like receptor 4 (TLR4) signaling via the phosphorylation of E2F1, and the downregulation of NANOG slows down hepatocellular carcinoma (HCC) progression induced by alcohol, a Western diet, and hepatitis C virus protein in mice." (PMID 36833320, 2023). "The authors found a novel lnc‐APUE (lncRNA accelerating proliferation by upregulating E2F1) that is upregulated in different cancer types, including hepatocellular carcinoma (HCC), and high lnc‐APUE level is associated with short recurrence‐free survival (RFS) of HCC patients." (PMID 33854885, 2021). "In hepatocellular carcinoma (HCC), c-Myc represses miR-122 expression that in turn indirectly inhibits c-Myc transcription by targeting the transcription factor Dp-2 (Tfdp2) and E2F transcription factor 1 (E2f1), which are essential for tumor development." (PMID 33672261, 2021). "Hepatoma cells transfected with E2F1 mutant with E2 motif deletion showed no luciferase activity induced by ISX expression." (PMID 27175585, 2016). "Importantly, human hepatocellular carcinomas (HCCs) recapitulate POH1 regulation of E2F1 expression, as nuclear abundance of POH1 is increased in HCCs and correlates with E2F1 overexpression and tumour growth." (PMID 26510456, 2015). "In hepatocellular carcinoma (HCC) studies, RRBP1 has been shown to serve a key role in high glucose-mediated tumor malignant progression through the E2F transcription factor 1 (E2F1)/RRBP1 signaling pathway." (PMID 41200062, 2026). "E2F Transcription Factor 1 (E2F1) is a transcription factor that plays a crucial role in the growth of many cancers, including hepatocellular carcinoma (HCC)." (PMID 40221814, 2025). "Overexpression of FIR in hepatocellular carcinoma (HCC) promotes tumor progression and dedifferentiation by stimulating FBP expression through Transcription Factor DP1/E2F Transcription Factor (TFDP1/E2F1)." (PMID 38539439, 2024). "The study reveals that TGFB1, E2F1, and HMBS could potentially serve as markers to identify the activation of the hepatic fibrosis signaling pathway and its corresponding biological function in the development of hepatocellular carcinoma." (PMID 38068980, 2023). "On the contrary, in hepatocellular carcinoma (HCC) cells Huh7 and colorectal cancer cells HCT116, SET7/9 stabilized E2F1 and up-regulated E2F1 downstream targets 42,43." (PMID 35069908, 2022).
hepatocellular carcinoma (continued). "Moreover, celecoxib was found to inhibit the growth of hepatocellular carcinoma cells by activating retinoblastoma protein (pRb) through its hypophosphorylation, thus repressing the DP1/E2F1 complex, and inducing apoptosis through the activation of caspase-3 and caspase-9." (PMID 34065773, 2021). "Genes up-regulated in hepatocellular carcinoma (HCC) from MYC and E2F1 double transgenic mice." (PMID 27732959, 2016). "Upregulated and nuclear-localized E2F1 (red), as the overexpressed ISX protein (green), was detected mainly in the nucleus (blue) of Hep 3B cells with forced ISX expression (yellow arrow) rather than in neighbor hepatoma cells without overexpressed ISX." (PMID 27175585, 2016).